CD52 (CD52 molecule)
Diseases named in the same sentence as CD52 in open-access papers (continued):
Sharing a sentence is not in itself a finding about the gene and the disease.
autoimmune disease (16 papers, 2011 to 2025). A disorder resulting from loss of function or tissue destruction of an organ or multiple organs, arising from humoral or cellular immune responses of the individual to their own tissue constituents. "Notably, the CD27/CD70 signaling pathway has been extensively linked to the promotion of autoimmune diseases, whereas CD52 has been associated with inflammation suppression, suggesting that DCs may exert a dual mode of action on T cells." (PMID 38596682, 2024). "The medical literature has documented instances where the onset of AHA has been linked to the use of alemtuzumab (anti-CD52), nivolumab (PD-1 inhibitor) and TNFα inhibitors, particularly etanercept and infliximab, which are commonly prescribed for various autoimmune disorders." (PMID 38846411, 2024). "Increased expression of CD52 and CD69 suggests a compensatory mechanism to overcome age-related decline in immune function and an excessive immune response associated with autoimmune diseases." (PMID 41226506, 2025). "CD19 and CD52, as critical targets for Immuno-oncology therapy, have demonstrated unique value in stem cell therapies for autoimmune diseases." (PMID 40777013, 2025). "Treatment with alemtuzumab induces depletion and reconstitution of circulating CD52+ B and T lymphocytes, resulting in sustained changes of the adaptive immunity, which is thought to contribute to the clinical benefits in autoimmune disorders." (PMID 35043373, 2022). "Alemtuzumab, the first therapeutic anti-CD52 antibody, has been shown to be effective in the treatment of autoimmune diseases such as RA and inflammatory bowel disease." (PMID 32802866, 2020). "The development of secondary autoimmune diseases in a subset of MS patients treated with B and T cell depleting alemtuzumab suggests an important role for CD52 in maintaining immune cell homeostasis." (PMID 33658999, 2020). "In contrast, anti-CD52 antibody has been suggested to lead to development of other autoimmune disease through the depletion of regulatory T cells." (PMID 28533776, 2017). "In addition, CD52 plays an important role in autoimmune diseases, such as systemic lupus erythematosus and systemic sclerosis." (PMID 37173673, 2023). "This population could be inhibited as a consequence of CD52‐mediated depletion and so could perhaps contribute the occurrence of secondary autoimmune disease that occurs following use of alemtuzumab in MS." (PMID 27925187, 2017). "The CD52+ Mo-Mp subtype expressed CD52, S100A9 and S100A8, which has been reported as a bi-directional regulator in inflammation of autoimmune diseases via T cell activation and Treg induction." (PMID 38601143, 2024). "Future studies are needed to evaluate the potential to leverage the inhibitory activity of CD52 on B cells as a novel therapeutic strategy for SLE and other autoimmune diseases." (PMID 33658999, 2020).
graft versus host disease (15 papers, 2013 to 2025). An immune system disorder that occurs after allogeneic hematopoietic stem cell transplant and is a reaction of donor immune cells against host tissues. "Current techniques knock out the T cell receptor α constant (TRAC) and CD52 genes/loci to reduce the risk of graft-versus-host disease (GvHD) and to avoid a host-versus-graft reaction, respectively." (PMID 38779672, 2024). "ALLO-715 contains a disrupted TCR alpha constant gene to reduce the risk of graft-versus-host disease (GvHD) and a disrupted CD52 gene to permit the use of ALLO-647, an anti-CD52 mAb, for selective and prolonged host lymphodepletion." (PMID 33879198, 2021). "The knockout of the TCR is intended to reduce the risk of graft-versus-host disease (GVHD) caused by donor T cells, whereas, knockout of the CD52 gene makes transplanted allogenic T cells resistant to the lymphodepleting agent alemtuzumab." (PMID 32093140, 2020). "Serotherapy comprising agents such as anti-thymocyte globulin, anti-T-lymphocyte globulin, and the anti-CD52 monoclonal antibody alemtuzumab is used widely to reduce the incidence of graft-versus-host disease (GvHD) after paediatric haematopoietic stem cell transplantation (HSCT)." (PMID 35071142, 2021). "Finally, there is recent evidence of the development of universal CAR-T-cells, where CD52 was knocked out in CAR-T cells, to prevent graft-versus-host disease by preventing CAR-T-cell loss upon anti-CD52 mediated depletion of immune cells during therapy." (PMID 32630096, 2020). "These modifications minimize graft versus host disease (GvHD) and allow anti-CD52 directed drugs in the lymphodepletion (LD)." (PMID 33670075, 2021). "It is an allogeneic, CD19-directed CAR T-cell product which has been modified to not express CD52 or the TCR alpha-chain, thereby minimizing the risk of graft versus host disease (GVHD)." (PMID 38817691, 2024).
breast cancer (13 papers, 2010 to 2025). A primary or metastatic malignant neoplasm involving the breast. "In breast cancer stromal tissue, CD52 has been linked to an expression signature of poor outcome, our results give further evidence of the potential of its overexpression as marker of immune cell invasion in breast tumors." (PMID 34189853, 2021). "It was reported that the immune-related gene CD52 was a prognostic biomarker for breast cancer, melanoma." (PMID 39256364, 2024). "Based on this finding, the CD52 antibody alemtuzumab can be a potential therapy specifically targeting metastatic breast cancer cells to further decelerate and even eliminate lymph node metastasis through re-activating T-cell immunity." (PMID 34611125, 2021). "Interestingly, though regarded as biomarkers on mature lymphocytes, CD52 was found to be highly expressed by metastatic breast cancer cells and contributed to the interaction between breast cancer cells and T cells in lymph nodes by binding to SIGLEC10." (PMID 34611125, 2021). "There should be a positive relationship between CD52 expression and activated memory CD4+ T cells in breast cancer." (PMID 36457341, 2022). "CD52 is known as a glycoprotein anchored in mature lymphocytes, the TCGA database showed a higher expression of CD52 in breast cancer cells compared with normal breast tissue, and our samples presented an even higher expression of CD52 in metastatic breast cancer cells of both TNBC and non-TNBC." (PMID 34611125, 2021). "For example, within the top highly expressed genes in claudin-low tumors versus all others, there are several wound response-related genes (i.e., CD28, CD52) that are not expressed by the breast cancer cell lines, potentially due to significant immune or stromal cell content in the tumor." (PMID 20813035, 2010).
relapsing-remitting multiple sclerosis (10 papers, 2015 to 2025). The most common clinical variant of multiple sclerosis, characterized by recurrent acute exacerbations of neurologic dysfunction followed by partial or complete recovery. "GD can be induced by immune reconstitution therapy (IRT) such as alemtuzumab (ALZ), a humanized monoclonal antibody against CD52, which is shown to be effective in the treatment of relapsing-remitting multiple sclerosis (RRMS)." (PMID 35651398, 2022). "Alemtuzumab, a humanized anti-CD52 monoclonal antibody, is approved for the treatment of active relapsing-remitting multiple sclerosis (MS)." (PMID 29033895, 2017). "Alemtuzumab, a humanized monoclonal antibody directed against the cell surface glycoprotein CD52, is licensed in Europe since October 2013 as treatment for adult patients with active relapsing-remitting multiple sclerosis (RRMS)." (PMID 27430352, 2016). "Alemtuzumab is a humanized monoclonal antibody against CD52 (cluster of differentiation 52) and is approved for the therapy of relapsing-remitting multiple sclerosis." (PMID 26204829, 2015). "Alemtuzumab, a highly effective anti-CD52 monoclonal antibody for relapsing-remitting multiple sclerosis (RRMS), acts mainly through the depletion and subsequent repopulation of T and B lymphocytes." (PMID 39021563, 2024). "Alemtuzumab is a monoclonal antibody targeting CD52 on the surface of immune cells, approved for the treatment of active relapsing-remitting multiple sclerosis (RRMS)." (PMID 37744364, 2023). "A striking example is autoimmunity following treatment of relapsing-remitting multiple sclerosis (RRMS) with the lymphocyte-depleting, humanized anti-CD52 mAb alemtuzumab (Lemtrada)." (PMID 31063156, 2019). "Alemtuzumab, an anti-CD52 monoclonal antibody, is a disease-modifying therapy (DMT) used to treat active relapsing-remitting multiple sclerosis (RRMS) in two cycles 1 year apart." (PMID 40831292, 2025).
lymphopenia (9 papers, 2009 to 2025). Reduction in the number of lymphocytes. "Regarding the usefulness of the algorithm, the action mechanism of alemtuzumab may be responsible for the very low sensitivity observed after induction therapy regarding peripheral lymphocytosis, due to lymphopenia caused by the anti‐CD52 antibody." (PMID 35894710, 2022). "Alemtuzumab is a humanised monoclonal anti-CD52-antibody, which leads to a profound and long-lasting lymphopenia due to depletion of T and B cells." (PMID 40676697, 2025). "Alemtuzumab is highly effective in the treatment of patients with relapsing multiple sclerosis (PwRMS) and selectively targets the CD52 antigen, with a consequent profound lymphopenia, particularly of CD4+ T lymphocytes." (PMID 35296069, 2022). "Alemtuzumab is a humanized monoclonal antibody against CD52, which leads to prolonged T cell lymphopenia and transient B cell lymphopenia." (PMID 33917860, 2021). "Although it is known to induce lymphocytopenia, little is known about the effects of the polyclonal rabbit antithymocyte globulin (rATG) or the monoclonal anti-CD52 antibody alemtuzumab on Natural Killer (NK) cells in detail." (PMID 19266059, 2009). "The relatively unaffected innate immune system as well as the limited immune cell depletion in primary and secondary lymphoid tissues (as observed in humanized CD52 mice) are believed to explain the low incidence of severe or opportunistic infections despite the long-lasting lymphopenia." (PMID 26966029, 2016). "However, no responses were observed in T-ALL patients, and the shared expression of CD52 among normal and malignant T-lymphocytes, expose patients to dangerous effects of lymphopenia, such as reactivation of cytomegalovirus, herpes simplex, or herpes zoster-latent infections." (PMID 35740552, 2022).
acute lymphoblastic leukemia (7 papers, 2017 to 2025). Leukemia with an acute onset, characterized by the presence of lymphoblasts in the bone marrow and the peripheral blood. "However, in patients with acute lymphoblastic leukaemia, this risk might be partly offset by the direct antileukaemic effect of alemtuzumab on CD52-positive B cells and T cells." (PMID 35358442, 2022). "Similarly, knocking TRAC region and CD52 gene in CAR-T cells by CRISPR/Cas9 avoided the host immune-mediated rejection for relapsed/refractory acute lymphoblastic leukemia (r/r ALL)." (PMID 35935840, 2022). "They all received immunotherapy: anti-CD38 mAb for multiple myeloma (daratumumab, n = 1), anti-CD52 mAb for T-cell chronic leukemia (alemtuzumab, n = 1), and anti-CD19 anti-CD3 bispecific mAb for acute lymphoblastic leukemia (blinatumomab, n = 1)." (PMID 36366475, 2022).
Autoimmunity (6 papers, 2017 to 2025). The occurrence of an immune reaction against the organism's own cells or tissues. "The inhibition of CD52 with alemtuzumab depletes circulating lymphocytes, which inadvertently carries a high risk of secondary autoimmunity." (PMID 41441522, 2025).
melanoma (6 papers, 2022 to 2025). A malignant, usually aggressive tumor composed of atypical, neoplastic melanocytes. "T-cell depleting agents, such as anti-thymocyte globulin and anti-CD52 monoclonal antibody, have historically been associated with an increased risk of DPTM, particularly PTLD and melanoma." (PMID 38610636, 2024). "Their studies showed that CD52 mRNA is expressed in a small subset of melanoma cells that co-express the immune checkpoint and that CD52 expression correlates with specific response characteristics to ICB in melanoma." (PMID 39274345, 2024). "Luka de Vos-Hillebrand and colleagues investigated the prognostic and predictive significance of CD52 mRNA expression in melanoma, examining its impact on prognosis, response to an immune checkpoint blockade (ICB), and elements of the tumor microenvironment (TME)." (PMID 39274345, 2024). "In the melanoma dataset, STModule identifies similar components from the two samples, including cancer cells (I), transition areas (II), lymphoid tissue (III; CD74, CD52, MS4A1), immune activities (IV-VI), CAFs, and melanocytes (GAPDH)." (PMID 40033360, 2025). "(CD52, CCL5, and IL32), and was resemble with a group of dysfunctional CD8 T cells recently identified in melanoma, esophageal squamous cell cancer and liver cancer." (PMID 35812401, 2022).
Sepsis (5 papers, 2021 to 2026). Sepsis is defined as life-threatening organ dysfunction caused by a dysregulated host response to infection. "Clinical qPCR validation confirmed that RPLP0 was significantly upregulated in sepsis patients, while CD52, RPS15A, and RPS18 were downregulated." (PMID 42291321, 2026). "CD52 is a therapeutic target and predictive biomarker for sepsis." (PMID 38892129, 2024). "Higher levels of PCT and CRP were produced after treatment with the CD52 monoclonal antibody alemtuzumab, similar to the sepsis brought on by Gram-negative bacteria." (PMID 39685604, 2024).
T-cell prolymphocytic leukemia (5 papers, 2017 to 2025). A slow-growing type of leukemia (blood cancer) in which too many lymphocytes are found in the bone marrow and/or blood. "Here, we aim to review the genetic and molecular underpinnings of T-prolymphocytic leukemia, as well as current treatment options, with a focus on the anti-CD52 monoclonal antibody alemtuzumab and JAK inhibitors." (PMID 40109866, 2025). "Marrow flow cytometry confirmed T-prolymphocytic leukemia with lymphocytes expressing CD2, CD3, CD7, CD52, and TCL-1." (PMID 31327318, 2019).
atherosclerosis (4 papers, 2022 to 2023). A disease characterized by the build-up of fatty material and calcium deposition in the arterial wall resulting in partial or complete occlusion of the arterial lumen. "The ROC curve suggests that CD52 and IL1RN showed favorable diagnostic value in distinguishing between atherosclerosis and control data in the GSE43292, GSE97210, and GSE100927 datasets." (PMID 37173673, 2023). "The immune-associated genes in both atherosclerosis and osteoporosis from WGCNA mainly included TREM1, CYBB, CCR1, CD83, CD52, IL7R, and THBS1." (PMID 35937806, 2022). "Thus, based on the results of the bioinformatics analysis, we speculate that changes in CD52 expression play an important role in atherosclerosis.​." (PMID 37173673, 2023). "Results showed significantly increased expression of CD52 and IL1RN in ox-LDL-treated cells, suggesting that CD52 and IL1RN were induced in atherosclerosis cell models." (PMID 37173673, 2023). "While this indicates that CD52 and IL1RN are highly expressed in foam cells, they still need to be further validated in vitro and in vivo to further explore their potential mechanisms in atherosclerosis." (PMID 37173673, 2023). "In addition, expression levels of CD52 and IL1RN in the atherosclerosis samples were also significantly higher than in the normal samples." (PMID 37173673, 2023). "Furthermore, by constructing a robust DEGs PPI network and integrating the 12 algorithms of cytoHubba, we identified two key genes, CD52 and IL1RN, and validated their performance in the diagnosis of atherosclerosis." (PMID 37173673, 2023). "​The role of CD52 in atherosclerosis has not been studied, but atherosclerosis is closely related to immunity and inflammation." (PMID 37173673, 2023). "​This study has established that CD52 and IL1RN may play a key role in the occurrence and development of atherosclerosis, which opens new lines of thought for further research on the pathogenesis of atherosclerosis." (PMID 37173673, 2023). "In addition to Dpp4, there was an upregulation of a number of inflammation‐related genes including Card8, Card16, Gzma, Prf1, Il2rg, Il32, Cd52, and Ccl4 in CD4+ T cells isolated from patients with atherosclerosis." (PMID 36683148, 2023).
COVID-19 (4 papers, 2021 to 2025). A disease caused by infection with severe acute respiratory syndrome coronavirus 2. "Specifically, in COVID-19, these genes were CD52, ISG15, and MMP9; in influenza, they included IFI44L, IFIT3, ISG15, and OAS1; and in HIV, OAS1 was identified." (PMID 38601162, 2024). "Specifically, in the COVID-19 patient’s B cells, we detected a substantial increase in the expression of CD52, CD74, CD22 and CD79B and a decrease in CXCR4, CD69, INFGR1, PTPRC and LAMP1 transcripts with respect to control-derived B cells." (PMID 34944610, 2021). "ACE (AUC: 0.923), CYP1A1 (AUC: 0.902), EME1 (AUC: 0.977), CD52 (AUC: 0.970), MYBL2 (AUC: 0.995), CDC25A (AUC: 0.998), BCL6 (AUC: 0.966) and CD3D (AUC: 0.955) showed relatively good diagnostic efficiency in distinguishing COVID-19 patients from healthy controls." (PMID 38978778, 2024). "Considering the significant alterations of NKeff cells subset in COVID-19 patients, a detailed assessment of the immunophenotype of NKeff cells subset was conducted, focusing on markers including CD69, KIR, CD52, CD226, NKG2D, and CD62L using flow cytometry." (PMID 40471558, 2025). "Our analysis revealed a trend towards elevated expression of CD69, KIR, and CD52, alongside diminished expression of CD226, NKG2D, and CD62L in patients who contracted COVID-19, when contrasted with those with T2D or control subjects." (PMID 40471558, 2025). "The role of the remaining eight key genes (ALDH1L, EME1, PYGL, NNMT, PHGDH, CD52, CD3D, and ESM1) in COVID-19 and sarcopenia has been less studied, emphasizing their importance in future research." (PMID 38978778, 2024). "Furthermore, when COVID-19 patients were compared with patients with T2D or control subjects, a trend was noted toward increased expression of CD69, KIR, and CD52 and decreased expression of CD226, NKG2D, and CD62L." (PMID 40471558, 2025).
experimental autoimmune encephalomyelitis (4 papers, 2017 to 2022). An autoimmune demyelinating disease of the central nervous system that is produced experimentally in animals by the injection of homogenized brain or spinal cord in Freund's adjuvant. "Relapsing experimental autoimmune encephalomyelitis was induced in ABH mice and immune cell depletion was therapeutically applied using mouse CD52 or CD4 (in conjunction with CD8 or CD20) depleting monoclonal antibodies." (PMID 27925187, 2017).
systemic lupus erythematosus (4 papers, 2020 to 2024). An autoimmune multi-organ disease typically associated with vasculopathy and autoantibody production. "This elevation seemed broad and not primarily driven by antibodies against known lupus antigens; however we detected non-significant trends of elevated CD52 in patients with anti-dsDNA antibodies (p = 0.141) and anti-RNP antibodies (p = 0.169)." (PMID 33658999, 2020).
T-cell leukemia (4 papers, 2016 to 2021). A malignant disease of the T-lymphocytes in the bone marrow, thymus, and/or blood. "YM155 alone or in combination with an anti-CD52 monoclonal antibody, alemtuzumab, were effective in adult T-cell leukemia with the combination showing enhanced tumoricidal activity." (PMID 27050416, 2016).
T-cell lymphoma (4 papers, 2018 to 2022). "At this point, only mAbs for CD20-positive B cell (Blontress®) or CD52 positive T cell lymphoma (Tactress®) are approved by the US Department of Agriculture and commercially available in the USA and Canada." (PMID 29459862, 2018). "A caninized mAb against the T-cell antigen CD52 (Tactress®) has been tested in two large, well-controlled studies in conjunction with cytotoxic chemotherapy for the treatment of canine T-cell lymphoma." (PMID 29459862, 2018).